IL5 (interleukin 5)
Diseases named in the same sentence as IL5 in open-access papers (continued):
Sharing a sentence is not in itself a finding about the gene and the disease.
eosinophilia (continued). "But the whole CEL characteristics with eosinophilia-associated end-organ infiltration needs oncoprotein F/P collaborated with additional IL-5 stimulation." (PMID 29029406, 2017). "Eosinophilia of the airway is a phenomenon associated with Th2 allergen-driven inflammation and with the presence of IL-5 produced by Th2 cells, but in fact, the eosinophils themselves are among the main producers of IL-5." (PMID 28628664, 2017). "AD is characterized as a Th2 disease with the abundant production of Th2 cytokines, such as interleukin IL-4, IL-5 and IL-13 associated with eosinophilia and elevated serum IgE level." (PMID 28434120, 2017). "Treatment with the anti-IL-5 monoclonal antibody mepolizumab has been shown to reduce bronchial tissue eosinophilia, in association with decreased TGF-β1 in BAL specimens, and reduced reticular basement membrane procollagen III, tenascin, and lumican." (PMID 28713812, 2017). "Both in humans and animals, inhibiting IL-5 with monoclonal antibodies (mAbs) can decrease circulatory and bronchoalveolar eosinophilia caused by an allergic challenge or chronic disease." (PMID 27053925, 2016). "When the authors blocked IL-10 action in the infected group, via monoclonal antibodies, the mice became susceptible to the hyperresponsiveness, with higher eosinophilia and higher IL-5 production." (PMID 27635405, 2016). "In this study we demonstrated that mice lacking both p110γ and δ exhibit increased eosinophil counts and elevated serum IL-5 and IgE levels in a basal state, suggesting that a deficiency of p110γ/δ causes IgE-hyperproduction and eosinophilia." (PMID 27442134, 2016). "It has been shown that IL-5 produced by CD4 T cells is required for eosinophilia in the context of cryptococcal infection and IL-5 overexpressing mice are highly susceptible to C. neoformans infection." (PMID 26252005, 2015). "SP-D gene deficient mice were found to exhibit hyper-eosinophilia and increased levels of IL-5 and IL-13 upon Aspergillus fumigatus allergen challenge, a response that was reversible by treating the mice with SP-D." (PMID 25848896, 2015). "Given the central role of IL-5 in eosinophil development and action, a number of studies have focused on blocking IL-5 and its effect on eosinophilia and the symptoms associated with allergic asthma." (PMID 23378838, 2013). "It is not uncommon for nonmyeloid malignancies such as T-cell lymphomas and Hodgkin's disease to be associated with secondary eosinophilia due to the production of cytokines such as IL-3, IL-5, and GM-CSF which promote eosinophil differentiation and survival." (PMID 24224106, 2013). "In many cases, eotaxin caused substantial airway eosinophilia and, in conjunction with IL-5, and IL-13, caused an even more marked increase in eosinophils." (PMID 22203879, 2012). "As IL-5 is implicated in contributing to eosinophilia, we also measured lung eotaxin (CCL11), a chemoattractant that promotes eosinophil recruitment to the lungs." (PMID 23031690, 2012). "Gleich syndrome is a disease characterized by recurrent angioedema associated with blood eosinophilia and elevated serum IL-5 and IgM levels (polyclonal IgM)." (PMID 23282419, 2012). "It is intriguing that despite this preponderance of data from natural infection in domestic animals and in laboratory models, IL-5 and eosinophilia are actually associated with an increased risk of recurrent infection with E. granulosus in humans." (PMID 22360486, 2012). "Expression of IL-4, IL-5 and IL-13 are associated with airway hypersensitivity, eosinophilia, abundant plasma cells and pathological changes in the lungs." (PMID 21765962, 2011). "In many cases, eotaxin caused substantial airway eosinophilia and in conjunction with IL-5 caused an even more marked increase in eosinophils." (PMID 21772663, 2011). "Mice that constitutively overexpress IL-5 have an increased eosinophilia that causes a more rapid clearance of L. sigmodontis." (PMID 20976099, 2010).
eosinophilia (continued). "Previous studies on atopic dermatitis suggest that skin lesions accompanied by topical eosinophilia and systemic IgE elevation are associated with Th2 cytokines (IL-4, IL-5, and IL-13)." (PMID 21197410, 2010). "The characteristic Th2-related cytokines (Il4, Il5, Il13) were markedly increased in AD-like lesions, while Il4 and Ccl11 expression was elevated to various extent in PN-like lesions appeared to be associated with dermal eosinophilia." (PMID 41229431, 2025). "By way of example, previous studies have reported a lower isolation rate of S. aureus in patients from China than in Caucasian patients, as well as a different pattern of association for IL-5, nasal polyps, and eosinophilia between European and Chinese patients." (PMID 39125792, 2024). "Therefore, we considered that the presence of IL‐5 is important in eosinophilia associated with renal cancer." (PMID 38966767, 2024). "TH2-associated cytokines such as IL-4, IL-5, and IL-13, which are often detectable in the presence of eosinophilia, may play a role in EDHM’s pathogenesis." (PMID 39219952, 2024). "For example, Eosinophilia was developed in mice infected by Aspergillus fumigatus, which was verified that eosinophil accumulation and collagen deposition were mainly associated with interleukin-5 (IL-5)." (PMID 38297325, 2024). "Furthermore, IL-13 has been linked to eosinophilia, where it functions in conjunction with IL-5 to facilitate eosinophil activation and migration." (PMID 39594470, 2024). "Interestingly, while anti-IL5 therapy (using Mepolizumab, Reslizumab, or Benralizumab) in patients with asthma decreased their BMI, blood hyper-eosinophilia was associated with a decreased risk of T2D in an adult cohort composed of both women and men in China." (PMID 38585275, 2024). "Finally, in an ovalbumin-induced murine model of allergic airway disease, NK-deficient mice had decreased airway inflammation and eosinophilia, decreased secretion of IL-4, IL-5, and IL-13, as well as diminished OVA-specific antibody production." (PMID 36250466, 2022). "In addition, the IL-4, IL-5 and Th2 responses associated with eosinophilia have been described in C. neoformans pneumonia, but little is known about these populations during C. gattii infection." (PMID 36145419, 2022). "IL-5 modulates the transcription of genes encoding in B-cell proliferation, cell survival, maturation, and effector activities, as well as innate and acquired immunological responses and eosinophilia." (PMID 36160850, 2022). "CD4+ T lymphocytes release IL-5, a key cytokine that attracts eosinophils to the inflammatory tissue sites and also contributes to increased blood eosinophilia in association with granulocyte-macrophage colony-stimulating factor (GM-CSF) under a Th2 environment." (PMID 36296298, 2022). "Here we show that Hp‐TGM could alleviate airway and lung tissue eosinophilia, in association with control of IL‐5 and IL‐33 cytokine levels at 24 h, or either IL‐4 and eotaxin‐1, or IL‐4 and IL‐13 responses in T‐cell mediated models." (PMID 35758054, 2022). "Similarly, clinical studies were unable to find an association between reduced eosinophilia by mepolizumab (IL-5 blockade) and airway function/hyperreactivity, although fewer exacerbations were observed." (PMID 34868033, 2021). "Bronchial biopsies from atopic asthma patients treated with anti-IL-5 (mepolizumab) showed an association between reduced airway eosinophilia and the significant reduction of biomarkers for airway remodeling such as RBM collagen, tenascin, and lumican deposition." (PMID 34576313, 2021). "Another hypothesis to consider is that low doses of anti-IL-5 biologics may cause worsening of airway eosinophilia through inducing immune-complex (IC) formation or complement consumption." (PMID 35126131, 2021). "Given that IL-33 induces type-2 cytokines from ILC2, the attenuated eosinophilia in ob/ob mice may have been associated with a decrease in IL-5, IL-13, and eotaxin." (PMID 34074279, 2021).
eosinophilia (continued). "Further clinical studies are warranted to determine whether benralizumab or other drugs targeted against IL-5/IL-5R may be useful in managing multiple conditions associated with eosinophilia." (PMID 33673870, 2021). "Interestingly, myeloid-specific IL4Rα-deficient (mye-IL4Rα−/−) mice had significantly reduced eosinophilia in the airspaces that was associated with reduced levels of IL-4 and IL-5 in the bronchoalveolar lavage fluid (BALF)." (PMID 34326406, 2021). "Indeed, the depletion or deficiency of IL-5 or CCL11 or blockade of IL-5R abrogates eosinophilia in several helminth infections." (PMID 33042162, 2020). "Our findings with administration of t-TUCB are similar to those from a previous study where OVA-challenged mice administered with t-TUCB demonstrated increased levels of EETs (5,6-, 11,12-, and 14, 15-) associated with decreased eosinophilia and reduced IL-4 and IL-5 levels." (PMID 31611798, 2019). "IgE secretion and IL-5-driven airway eosinophilia have also been associated with AAD." (PMID 30845208, 2019). "In accordance with these findings, we see IL-33 treatment increases IL-5 levels during C. difficile infection, and adoptive transfer of ILC2s causes increased eosinophilia in the colon during C. difficile infection in addition to preventing CDI-associated weight loss and mortality." (PMID 31221971, 2019). "The IL-5 gene may play a pivotal role in blood eosinophilia associated with atopic dermatitis (AD) and may contribute to a genetic susceptibility." (PMID 29751492, 2018). "Eosinophil infiltration into tissues is usually accompanied by eosinophilia, which may be transient, and is often caused by an increase in serum IL-5 or tissue IL-5." (PMID 28496445, 2017). "Following airway allergen exposure, the development of airway eosinophilia is associated with increased IL-5 expression in the sputum, elevated concentrations of IL-5 in luminal fluid and serum, and a heightened capacity of airway cells for ex vivo generation of IL-5." (PMID 25829869, 2015). "Eosinophilia is rare and is usually due to IL-5 secretion in lung cancer, although the definitive cause in the present patient was unknown." (PMID 25013473, 2014). "Typically, it is believed that the eosinophilia is caused by the production of various cytokines, such as interleukin (IL)-5, IL-3, and granulocyte–macrophage colony–stimulating factor (GM-CSF) by B cell lymphoma cells or non-neoplastic T lymphocytes activated by B cell lymphoma cells." (PMID 25273521, 2014). "Indeed, hybrid Th1/2 cells from the lungs contained fewer IL-13 and IL-5 producers than Th2 cells, associated with milder eosinophilia and reduced mucus production." (PMID 23976880, 2013). "Furthermore IL-5 is positively associated with eosinophilia (r = 0.119, p = 0.050), while IFNγ/IL-5 demonstrates an inverse association to eosinophil counts (r = −0.119, p = 0.030)." (PMID 21179211, 2010). "Indeed, in mouse models, IL-5 overexpression was associated with eosinophilia." (PMID 40305195, 2025). "Eosinophilia is one of the common features of hypersensitivity reactions caused by the sequential release of antigen-activated Th2 cells and key cytokines, including the release of key cytokines such as IL-5, which trigger eosinophil proliferation, accumulation, and function." (PMID 37082379, 2023). "Moreover, other eosinophils, T cells, macrophages, hepatocytes, and Kupffer cells release in situ macrophage migration inhibitory factor (MIF), a molecule that participates in the IL-5-driven maturation of eosinophils and tissue eosinophilia associated with S. mansoni infection." (PMID 36296298, 2022).
eosinophilia (continued). "Therefore, the inhibition of asthmatic symptoms by PS + CR may be associated with the reduction of IL-4 and IL-5 production and the eosinophilia aggregation into the lungs, as comparable to DEXA (3 mg/kg), at oral dose level of 1,000 mg/kg, once again." (PMID 32190091, 2020). "Dupilumab (targeting IL-4/IL-13) and mepolizumab (targeting IL-5) have shown promising results in reducing mass size and eosinophilia in patients who respond poorly to conventional therapies." (PMID 41527674, 2026). "Infection of C57BL/6 mice triggered local and systemic eosinophilia that was driven by type 2 innate lymphoid cells and interleukin-5." (PMID 41813911, 2026). "Mechanistically, allergen-sensitized Th2 cells produce pro-inflammatory cytokines such as IL-4, IL-5, and IL-13, thereby driving airway eosinophilia and chronic inflammation." (PMID 41422349, 2025). "Cholic acids precipitated stromal IL-33 release, subsequently activating ILC2s to secrete IL-5, thereby promoting tissue eosinophilia and inflammation." (PMID 41313018, 2025). "While IL-5 is produced by T cells in both lines, the level of eosinophilia differs between the two mouse lines, with CD3.IL-5tg mice having higher baseline circulating eosinophil levels than CD2.IL-5tg (40%–60% versus 20%–30%, respectively)." (PMID 41050650, 2025). "IL-10 is described as an inhibitor of eosinophilia by suppressing the production of IL-5 and GM-CSF, indirectly influencing the apoptosis and proliferation of eosinophils." (PMID 41574188, 2025). "The innate response to STHs comprises the release of cytokines, such as IL-4, IL-5, and IL-13, which drive eosinophilia, mast cell activation, and IgE production, which are key mechanisms required for the expulsion of parasites." (PMID 40872306, 2025). "The cytokine IL-5 generated by T-cells is crucial for the emergence of eosinophilia and is particularly effective in stimulating this cell type." (PMID 41179937, 2025). "Eosinophilia is driven by IL-5 and other Th2 cytokines, which promote eosinophil proliferation and survival." (PMID 41583474, 2025). "In vivo, CD4-specific conditional IP KO mice (CD4Cre+IPflox) exhibited exacerbated lung inflammation following exposure to Alternaria alternata extract, marked by increased IL-5 and IL-13 production, enhanced eosinophilia, and elevated mucus production." (PMID 40587812, 2025). "Recently, many have reported that IL-5 deletion leads to airway eosinophilia because of IL-5’s ability to control the eosinophil recruitment, maturation, activation, and inhibition of apoptosis." (PMID 39861052, 2025). "The mechanism of reactive eosinophilia in hypersensitivity reactions is driven by IL-5-mediated eosinophilopoiesis, mast cell activation, and IgE-linked Th2 inflammation." (PMID 41552084, 2025). "For example, in a recent study we showed that extreme hyper-eosinophilia, induced by over-expression of IL-5, slows muscle regeneration and accelerates fibrosis in mdx mice." (PMID 39900735, 2025). "ANCA-negative EGPA displays a stronger type 2 inflammatory profile, with elevated IL-5 levels and prominent tissue eosinophilia." (PMID 41303621, 2025). "The neoplastic cells in CHL (i.e. Reed-Sternberg cells) have been shown to contain the mRNA coding for IL-5, suggesting that direct IL-5 production by these cells contributes to the eosinophilia." (PMID 39873807, 2025). "While markers for identifying the T2-high phenotype are well established, IL-4, IL-5, IL-13, IgE, eosinophilia, and high FeNO levels, evidence for T2-low biomarkers remains limited." (PMID 40003269, 2025). "Activated Th2 cells release cytokines, including IL-4, IL-13, and IL-5, inducing eosinophilia in tissues and peripheral blood." (PMID 39521708, 2025). "In particular, IL-5 plays a central role in inducing eosinophil activation and recruitment to sites of infection, while eotaxin also promotes eosinophilia." (PMID 41312315, 2025).
eosinophilia (continued). "It is well established that eosinophilia is related to type-2 inflammation, with eosinophils produced in response to IL-5 and further regulated in response to IL-4 and IL-1330." (PMID 40846755, 2025). "Overall, these findings suggest a direct relationship between TARC, IL-5, and eosinophilia in PTCL-NOS NTFHL-AI, and ATLL." (PMID 39873807, 2025). "Specifically, Th2-mediated inflammation is predominant, characterized by elevated interleukin (IL)-4, IL-5, and IL-13, leading to eosinophilia, IgE overproduction, and skin barrier dysfunction." (PMID 40831866, 2025). "Within the ILC family, group 2 ILCs (ILC2s), in particular, contribute significantly to type 2 inflammation through their rapid production of cytokines such as IL-5 and IL-13, promoting airway eosinophilia and airway hyperreactivity." (PMID 40355861, 2025). "These aberrant T cells chronically stimulate IL-5 production, resulting in persistent eosinophilia and infiltration of eosinophils into target tissues, with the skin, lungs, and gastrointestinal tract most affected." (PMID 41488087, 2025). "In AD, increased activity of type 2 innate lymphoid cells (ILC2) is also observed, which, like Th2 lymphocytes, produce interleukin 5 (IL-5) and IL-13, contributing to tissue eosinophilia and chronic inflammation." (PMID 40565306, 2025). "Eosinophilic/ANCA-negative: favor IL-5 or IL-5Rα inhibition, with escalation to IL-5Rα agents (e.g., benralizumab) in patients with persistent eosinophilia, relapse after IL-5 therapy, or preference for single-dose administration every 4 weeks." (PMID 41303621, 2025). "A patient with NSCLC, leukocytosis, eosinophilia, high blood IL-5 levels, and a lymph node was identified in a previous study." (PMID 41179937, 2025). "Reactive eosinophilia represents a polyclonal increase in mature eosinophils driven by cytokines such as interleukin (IL)-3, IL-5, and granulocyte-macrophage colony-stimulating factor produced in response to immunological stimulation." (PMID 41552084, 2025). "In contrast to SLPI KO mice treated with the control solvent, BPTI-treated SLPI KO mice showed reduced airway inflammation, fewer total BAL cells, and lower ratios of eosinophilia and Th2 cytokines, including IL-5 and IL-13, in BAL fluid." (PMID 40546642, 2025). "As a matter of fact, in Western Countries, CRSwNP is well known to be predominantly characterized by Type 2 inflammation with pronounced eosinophilia and the presence of high levels of Type 2 cytokines, such as IL-4, IL-5 and IL-13." (PMID 41295249, 2025). "Eosinophilic adenoiditis or otitis media, defined by IL-5 or IL-13 expression and tissue eosinophilia, are more likely to respond to corticosteroids or anti-IL-5 biologics." (PMID 40868875, 2025). "Mepolizumab prevents IL-5 from binding to its receptor, thereby inhibiting the recruitment and activation of eosinophils, leading to resolution of eosinophilia and improvement in symptoms." (PMID 40755600, 2025). "Lymphocytic variant hypereosinophilic syndrome (L-HES) is a rare subtype of hypereosinophilic syndrome driven by aberrant T-cell clones that promote eosinophilia through interleukin-5 (IL-5) overproduction." (PMID 41488087, 2025). "In ATLL, high serum IL-5 levels are present in a subset of cases, correlating significantly with eosinophilia." (PMID 39873807, 2025). "IL-5 is a prominent cytokine in eosinophil development and IL-5 overexpressing mice show a massive eosinophilia." (PMID 40276331, 2025). "It is known that IgE and IgG4 responses are elicited by IL-4, while IFN-γ and eosinophilia are stimulated through IL-3 and IL-5." (PMID 40041800, 2025). "These cells produce transforming growth factor, IFNγ (mediator of fibrosis), IL-4, and IL-5 (mediators of IgE and eosinophilia)." (PMID 39051325, 2024). "Mepolizumab, a monoclonal antibody targeting interleukin-5, is used to treat severe eosinophilic asthma and other eosinophilia-related conditions." (PMID 39574910, 2024).